IL1B (interleukin 1 beta)
Diseases named in the same sentence as IL1B in open-access papers (continued):
Sharing a sentence is not in itself a finding about the gene and the disease.
COVID-19 (continued). "While TNF-α, IL-1β, and IL-6 are the most important cytokines in this damaging process, in the later phase of critical infectious disorders, such as severe COVID-19 patients, the systemic levels of IL-4, IL-10, and IL-13 may also increase." (PMID 36671034, 2023). "We conclude that hypercoagulation and the cytokine storm in severe COVID-19 are linked through the spike-CD42b interaction that activates platelets, the CD40L-CD40 and the P selectin–PSGL-1 interactions that bind them to monocytes, and the strong induction of IL-1β in the monocytes." (PMID 34964720, 2022). "The mechanism of the nervous system manifestations of COVID-19 may be that SARS-CoV-2-related cytokines such as IL-1b, IL-17, IL-6, and TNF alter the permeability of the blood-brain barrier, which makes SARS-CoV-2 can reach the brain and recognize ACE2 directly affects brain cells." (PMID 35774397, 2022). "Furthermore, in COVID-19, increased levels of IL-1β may indicate inflammasome activation and pyroptosis of host infected cells." (PMID 36111104, 2022). "IL-1β and IL-18 are direct results of inflammasome activation, our analysis showed that they were increased in the COVID-19 group when compared to the control (p < 0.0005) group and that IL-18 was increased in the COVID-19 group even when compared to the H1N1 group (p < 0.0001)." (PMID 36361818, 2022). "Elevated levels of IL-6, IL-8, and IL-10 were associated with the disease severity of COVID-19, and elevated levels of IL-1β, IL-6, and IL-8 were related to the prognosis of COVID-19 patients, which could be used to evaluate COVID-19 patients' disease severity and prognosis." (PMID 35540724, 2022). "Studies have shown that S-protein in SARS-CoV-2 could elicit inflammasome formation and IL-1β production in macrophages from COVID-19 patients, and further exploration revealed that this process needed non-specific activation of monocytes in vivo to trigger NLRP3 inflammatory signaling." (PMID 36505489, 2022). "The aim of this study was to determine the association of Gal-1 and innate immunity cytokines such as IL-1β, IL-6, IL-10, IL-23, IL-33 with disease severity, alongside with clinical, biochemical features and Chest X-rays (CXR) lung findings in 210 patients with COVID-19." (PMID 35075140, 2022). "Increased lung macrophage density in COVID-19 is closely associated with ALI, and scRNA-Seq studies show proinflammatory macrophage gene expression signatures in COVID-19 with distinctly high expression of IL-1β and chemokines that may propagate lung inflammation." (PMID 35446789, 2022). "Therefore, we have then evaluated the levels of TNFα and IL-1β in saliva of COVID-19 patients." (PMID 36136963, 2022). "Interestingly, large IL-1β secretion upon stimulation has also been reported in macrophages derived from outpatients with COVID-19, suggesting that innate immunity dysregulation may also occur in mild disease or asymptomatic infection." (PMID 36209522, 2022). "Therefore, patients having low levels of IL-1β in SARS-CoV-2+ BAL might be prone to develop fatal COVID-19 as compared to those with high levels." (PMID 36248831, 2022). "Cytokine dysregulation (particularly transforming growth factor-β (TGF-β), Tumor Necrosis Factor (TNF)-α, Interleukin (IL)-1β, Interferon (IFN)-γ, IL-6, and IL-10) are known to be associated with psychiatric disorders, and have been shown to be elevated in patients with COVID-19." (PMID 35053059, 2022). "In addition, the enrichment results showed that the pathogenic processes of RA, AS and GA were all related to the targets of TNF, IL-6, IL-1β and part of the Coronavirus disease signaling pathway, and there were some common pathogenesis, targets and biological processes with COVID-19." (PMID 35935817, 2022).
COVID-19 (continued). "PGE2 may participate in the conversion of pro-inflammatory interleukins (e.g., IL-1β and IL-6) to anti-inflammatory interleukins synthesized by M2 macrophages (e.g., IL-10), which may explain the significant increase in IL-10 in patients who survived COVID-19." (PMID 36233111, 2022). "Therefore, we hypothesized IL-1β to be a potential therapeutic target for suppressing acute hyperinflammation and therefore treat patients at risk of developing ARDS related to COVID-19." (PMID 35925914, 2022). "Interestingly, the most prominent immunity change occurring in COVID-19 patients indicates the elevation of these pro-inflammatory cytokines, including TNF-α, IL-1β, and IL-6, causing the prevalent cytokine shift, also called the cytokine storm, in patients with severe or terminal disease condition." (PMID 35204178, 2022). "Furthermore, COVID-19 dysbiosis causes an increase in inflammatory cytokines such as IL-6, TNF-α, and IL-1β, which might be one of the important predisposing factors for severe infection." (PMID 36532032, 2022). "Interestingly, NETosis was also shown to activate pyroptosis, through induction of NLRP3, suggesting that during COVID-19 NETosing neutrophils might also contribute to IL1-β and IL-18 secretion." (PMID 35244141, 2022). "Given that elevated concentrations of IL-1β and IL-6 are associated with adverse clinical outcomes in COVID-19,9, 10 targeting the NLRP3 inflammasome (which is responsible for the maturation and secretion of IL-1β) might reduce related complications in patients at risk of cytokine activation." (PMID 34051877, 2021). "Hence, we speculate that increased IL-1β and IL-6 may worsen the disease in colorectal cancer patients with COVID-19." (PMID 34863291, 2021). "Finally, increased IL-17 production by Th17 cells in COVID-19 patients has broad pro-inflammatory effects through the upregulation of pro-inflammatory cytokines like G-CSF, IL-1β, IL-6, TNFα, as well as chemokines like MIP2A, IL-8, IP10, MIP3A, and matrix metalloproteinases." (PMID 34512643, 2021). "Likewise, the IL-1β blockade by anakinra improves COVID-19 outcomes in 72% of patients." (PMID 34027897, 2021). "Both IL-1β and IL-6 may play a role in this process, and cytokine-modulating therapies are now being tested in COVID-19 clinical trials." (PMID 33319166, 2021). "Finally, we tested the hypothesis that elevated IL-1β and IL-6 transcriptional activity in blood could predict clinical outcome in COVID-19." (PMID 33319166, 2021). "In COVID-19, damage-associated molecular patterns (DAMPs) generated during the lytic viral replication cycle signal through the inflammasome of the NOD-3-like receptor protein (NLRP3), resulting in the processing of the IL-1β precursor molecule, which is then secreted by macrophages." (PMID 34066385, 2021). "Interestingly, G-CSF, IL-1β and IL-6 were still elevated in post-COVID-19 compared to HC." (PMID 34572439, 2021). "Severe COVID-19 is characterized by a marked hyperinflammatory response resulting in a cytokine storm, with dysregulated production of proinflammatory cytokines (e.g., IL-1β and IL-6), resulting in significant lymphopenia, C-reactive protein increase, and a profound vascular dysfunction." (PMID 34903264, 2021). "In patients with COVID-19 hospitalized in intensive care units, elevated serum levels of IL-1β, IL-7, IL10, IL-17, IL-2, IL-9, Th17, IFN-γ, GM-CSF, G-CSF, IL-8, TNF-α, MIP1B, MCP1, MIP1A, and IP10 were observed, suggesting that the relation between periodontitis and COVID-19 may be established." (PMID 34068221, 2021). "The first-line signals including interferon (IFN) signals and NOD-like receptor family pyrin domain containing 3 (NLRP3) inflammasome may be the most dominant, explained by the uncoordinated IFN responses that amplify TNF/IL-1β-centered hyperinflammatory signatures in severe COVID-19 patients." (PMID 34650550, 2021).
COVID-19 (continued). "Moreover, R. crenulata might play an anti-inflammatory and immunoregulatory role in the cytokine storm of COVID-19 by acting on IL-1β, IL-6 and TNF-α." (PMID 34313585, 2021). "Finally, the overexpression of v-miRNA-N-28612 in PBMCs in cell culture upregulated IL-1β, caspase 1, and NLRP3, which are markers of the inflammasome, suggesting that SARS-CoV-2 ncRNAs can directly mediate hyperinflammation, a hallmark of COVID-19." (PMID 34564316, 2021). "One of the main causes of death from COVID-19 is acute respiratory distress syndrome (ARDS), and the main mechanism of ARDS is the “cytokine storm,” which is caused by immune effector cells releasing large amounts of pro-inflammatory cytokines (e.g., TNF-α, IFN-γ, IL-1β, IL-6, IL-12)." (PMID 33815131, 2021). "Moreover, it is speculated that neutrophil extracellular traps (NETs)-IL-1β loop was activated in severe COVID-19 patients, amplifying the generation of NETs and IL-1β that accelerated the progress of CRS." (PMID 34766001, 2021). "Colchicine works by interfering with COVID-19 related manifestations such as hyper-inflammation, and inhibits inflammasome activation, neutrophil chemotaxis and the production of pro-inflammatory cytokines such as interleukin-1beta (IL-1β) and interleukin-18 (IL-18)." (PMID 33681243, 2021). "In agreement with this study, these findings indicated the importance of IL6, TNF and IL1B hub-high traffic genes, considered potential targets (individually or in combination) for development of effective therapeutic immunomodulation strategies to manage COVID-19 hyperinflammation." (PMID 34975885, 2021). "In addition, in the same experimental setting we found a remarkable production of inflammatory cytokines such as IL-6, TNF-α and IL-1β, which are well-recognized players of the cytokine storm occurring in COVID-19 patients, while IL-12p70 level was unchanged in SARS-CoV-2-stimulated PBMC." (PMID 34473805, 2021). "Therefore, we hypothesized that uncontrolled oxidative stress may form a positive feedback loop exacerbating NLRP3-inflammasome activation and the production of pro-inflammatory cytokines, such as IL-1β, during COVID-19." (PMID 35095880, 2021). "Increased levels of IL-1β in COVID-19 may point to inflammasome activation." (PMID 32961074, 2020). "Moreover, acute release of IL-1β has been described as a key inflammatory event in patients with COVID-19 that could also potentiate bradykinin-induced vascular permeability." (PMID 33327440, 2020). "Therefore, probing the role of IL-1β and its inhibition might lead to reduced inflammatory signaling, thus reducing lung injury in ARDS associated with severe COVID-19." (PMID 32655582, 2020). "Indeed, they observed a “core COVID-19 signature” shared by both moderate and severe groups of patients defined by the following inflammatory cytokines that positively correlated with each other; these included: IL-1α, IL-1β, IL-17A, IL-12 p70, and IFN-α." (PMID 33363221, 2020). "We have previously shown the neuroprotective potential of naringenin through modulation of inflammatory mediators (NF-κB, TNF-α, IL-1β, etc) and microglia activation in the CNS, thereby it could mitigate the neuronal signs of COVID-19 mediated by the inflammatory mediators." (PMID 33708124, 2020). "Similarly to SARS-CoV, pyroptosis may be triggered during COVID-19 leading to major IL-1β production and uncontrolled cytokine release." (PMID 32824753, 2020). "Thus, employing drugs already in clinical use, such as simvastatin, could offer a therapeutic strategy for decreasing bradykinin- and/or IL-1β-induced pulmonary edema in patients with COVID-19." (PMID 33327440, 2020). "However, it is worth noting that most of the currently tested immunomodulatory agents (especially anti-IL-6, anti-IL-1β, and anti-TNFα) have been put forward despite gaps in our understanding of the immune response behind COVID-19 ARDS, especially within the pulmonary compartment." (PMID 33138839, 2020).
COVID-19 (continued). "In serum samples, soluble TLR-2 and TLR-4, IL-1β, IL-4, IL-6, Il-10, IFN-α, and TNF-α levels were significantly decreased in patients with coronavirus disease-19 (COVID-19) as compared with other viruses (p < 0.05 in each)." (PMID 41766850, 2026). "This analysis shows that several inflammatory and viral cytokines remain elevated beyond the acute phase and are associated with cognitive deficits, including IL-6, IL-13, IL-8, IL-1β, TNFα, and MCP1 in long-term post-COVID-19 patients." (PMID 41516418, 2026). "During SARS-CoV-2 infection, monocytes and macrophages detect viral particles and produce IL-6, IL-1β, and IFN-π/IL-27 through TLR, NF-κB activation, and inflammasome assembly, contributing to acute respiratory distress syndrome (ARDS) and severe COVID-19." (PMID 40934228, 2025). "For example, SREBP2 activation is elevated in monocytes from COVID-19 patients, and its inhibitor, Fatostatin, suppresses the expression of pro-inflammatory cytokines such as TNF-α, IL-1β, and IL-6." (PMID 41134862, 2025). "Cytokine storms, characterized by an excessive release of IL-6, IL-1β, and TNF-alpha, remain a central determinant of disease severity in COVID-19." (PMID 40497938, 2025). "In the first phase of the study, participants in the acute phase of COVID-19 presented patterns of elevated inflammation in the form of high concentrations of cytokines such as TNF (TNF–α), LTA (TNF–β), IL–1β, IL–4, IL–6, IL–8, IL–13, and interferon (IFN) –α2." (PMID 40217938, 2025). "In severe COVID-19, NLRP3 activation in AMs shifts from a protective function to a pathological one, serving as a central amplifier of the cytokine storm (e.g., IL-1β, IL-18)." (PMID 41176818, 2025). "Some changes were seen solely in COVID-19, including MDC versus MIP-1α (p < 0.01); TNF-α versus IL-1-β (p < 0.06); MCP4 versus TARC (p < 0.0001)." (PMID 40723800, 2025). "We compared IL-1β, IL-1Ra and IL-6 mRNA production and release between IMHL patients with worsening SNHL after COVID-19 vaccination or infection (COVID (+)) with IMHL patients with worsening SNHL unrelated to COVID-19 (COVID (-))." (PMID 40329195, 2025). "This disruption contributes to the hyperinflammatory response seen in severe COVID-19 cases, which is marked by elevated levels of cytokines such as IL-6, TNF, and IL-1β." (PMID 40431622, 2025). "The analysis of cytokine profiles in pediatric patients with COVID-19, MIS-C, and healthy children revealed notable differences in levels of IL-1β, IL-6, IL-8, IL-12, TNF-α, and IFN-α levels." (PMID 40066463, 2025). "IL1B, IL6, and TNF are pro-inflammatory cytokines that contribute to the cytokine storm observed in severe COVID-19 cases, leading to acute respiratory distress and systemic inflammation." (PMID 41471341, 2025). "COVID-19's cytokine storm, characterised by IL-6, TNF-α, and IL-1β elevation, damages the neurovascular unit and increases vascular permeability." (PMID 41503306, 2025). "Residents of EA with COVID-19 and FLS had higher production of IL-12p70, IL-6, IL-1β, IL-2, and IL-1ra compared to residents of NEA, as well as an increased production of IL-10 in COVID-19 patients." (PMID 40165959, 2025). "The primary objective of this study was to investigate the correlation between genetic variations in IL1B, IL6, TNF, and critical outcomes of COVID-19." (PMID 40506975, 2025). "The resulting network revealed several highly connected hub proteins, including IL1B, IL6, TNF, ACE, and REN, which are central regulators of inflammatory and cardiovascular pathways known to play key roles in COVID-19 pathogenesis." (PMID 41471341, 2025). "In patients with the PAP phase of COVID-19, an increase in proinflammatory cytokines, namely, IFN-α, TNF-α, G-CSF, IL17A, IL-6, IL1-β, and IL-13, has been confirmed in a number of studies." (PMID 40002929, 2025).
COVID-19 (continued). "This allows NF-κB to enter the nucleus and trigger the production of pro-inflammatory cytokines such as IL-6, IL-1β, and TNF-α, which are notably elevated in patients with severe COVID-19." (PMID 40219044, 2025). "The analysis of cord blood samples at Early and Intermediate convalescent COVID-19 showed increased levels of CCL11, CCL3, CCL4, CCL2, IL-1β, IFN-γ, IL1-Ra, G-CSF, and IL-7 and a decrease of IL-10 and IL-2 as compared with HC." (PMID 40821818, 2025). "A study that administrated 10 g of glutamine thrice daily found decreased IL-1β, TNF-α, and hs-CRP in COVID-19 outpatients." (PMID 40002722, 2025). "In support of this second conclusion, we failed to observe any significant IL-1β mediated inflammation in the COVID -SSNHL group suggesting either non-IL-1β -mediated inflammation or, more likely, the patients experienced a SSNHL that is unrelated to COVID-19." (PMID 40329195, 2025). "All COVID-19 patient groups presented significantly higher concentrations of inflammatory cytokines, such as s-TNF-α, s-IL-1β and s-IL-6, compared to controls." (PMID 39862311, 2025). "Systemic inflammation in COVID-19 triggers the release of pro-inflammatory cytokines (IL-6, TNF-α, IL-1β), impairing cardiac function directly and by promoting inflammatory cell infiltration." (PMID 40142859, 2025). "Critical COVID-19 cases showed higher levels of inflammatory markers (Bilirubin, D-dimer, PCR, and urea, as well as IL-8, IL-10, TNF-α, INF-α, IL-1β, IL-17A, IL-23, IL-6) than moderate and severe groups." (PMID 39861879, 2025). "The consistent increase in ICAM1, MCL1, IL1β, and S100A12 expression in neutrophils from severe alive to severe dead patients underscores the critical role of neutrophils in COVID-19 severity." (PMID 39928675, 2025). "Hence, IL-1β could serve as a key marker for targeted treatment in patients with COVID-19." (PMID 41155463, 2025). "Multiple lines of evidence in COVID-19 show NLRP3 priming/activation in circulating leukocytes and tissues, with increased IL-1β correlating with severity and hypercoagulability." (PMID 41010381, 2025). "In the case of COVID-19, SARS-CoV-2 infection triggers a cascade of molecular disturbances, including excessive cytokine release (IL-6, TNF-α, and IL-1β), microglial activation, and oxidative stress, leading to neuroinflammation and neuronal dysfunction." (PMID 40126810, 2025). "Moreover, the anti-inflammatory properties of Febuxostat, through inhibition of the JAK/STAT and NF-κB pathways and subsequent reduction in pro-inflammatory cytokines such as IL-1β, IL-6, and TNF-α, may underlie its protective effects against COVID-19-related hyperinflammation and organ damage." (PMID 41235116, 2025). "Periodontitis and COVID-19 share several common inflammatory pathways, such as the NLRP3/IL-1β and IL-6 signaling pathway." (PMID 40406515, 2025). "Results showed that levels of IL-1β, IL-6, and TNF-α were significantly elevated after treatment with COVID-19 EVs." (PMID 39475319, 2024). "In particular, a relationship between COVID-19 aggravation and rs10754558 NLRP3, rs6509365 CARD8, rs2043211 CARD8, rs16944 IL1B, and rs755622 MIF have been described." (PMID 38612539, 2024). "Thus, the local production and release of IL-1β from human vascular cells and monocytes stimulated by the S protein may contribute to vascular dysfunction in the context of COVID-19, favoring vascular inflammation and perhaps amplifying and aggravating pre-existing vascular lesions." (PMID 38225643, 2024). "As a part of the innate immune response to COVID-19 the NLRP3 inflammasome is generated, which stimulates the release of interleukin 1β (IL-1β), IL-18, and gasdermin D (GSDMD), ultimately leading to pyroptosis of the infected cell." (PMID 40603504, 2024).